CXCL13 (C-X-C motif chemokine ligand 13)
Diseases named in the same sentence as CXCL13 in open-access papers (continued):
Sharing a sentence is not in itself a finding about the gene and the disease.
tumor (continued). "Interestingly, the production of CXCL13 by Tfh and Tph cells varies by tumor type and organ." (PMID 37788648, 2024). "Thus, our results indicate that CXCL13 can induce sICAM‐1, and sICAM‐1 enhances T cells' proliferation and their effector function and reduces tumor mass, suggesting the potential of sICAM‐1 as a new anti‐tumor therapy." (PMID 37097643, 2023). "In addition, CXCL13 depletion was confirmed in tumor tissues." (PMID 37097643, 2023). "We found that CXCL13 gene mutations did not affect its expression in any tumor type evaluated." (PMID 35141160, 2022). "Therefore, while CXCL13 in the tumour microenvironment might indicate B‐cell infiltration, tumour CXCR5 expression (rather than the TLS) could have a pro‐tumourigenic effect." (PMID 35218154, 2022). "Therefore, we analyzed the expression of murine CXCL13 in BM tissue of tumor-bearing mice." (PMID 36217194, 2022). "Particularly, the signaling of CXCL13 through its receptor, CXCR5, has recently been associated with promalignant intracellular pathways such as PI3K/AKT, MEK/ERK and Rac-GEF/Rac, leading to cell survival, proliferation and migration in different tumor entities." (PMID 36077611, 2022). "Chemokines involved in the recruitment of multiple immune cell subsets (Cxcr4, Cxcl13, Ccl22) were upregulated in parallel with the co-stimulatory molecules Icos and the checkpoint receptor Ctla4, suggesting complex immunological changes in the tumor microenvironment (TME) in response to treatment." (PMID 34445452, 2021). "Moreover, we observed significantly lower microvessel density in CXCL13-overexpressing 4T1 tumor, and this was supported by one previous study that CXCL13 modulated angiogenesis by inhibiting fibroblast growth factor 2-induced chemotaxis, proliferation, and survival of endothelial cells." (PMID 35693216, 2021). "Furthermore, this study showed tumour-specific T cell responses, with enrichment and clonal expansion of pro-inflammatory CXCL13+ BHLHE40+ TH1-like cells in tumours with microsatellite instability, but moderate enrichment for Th17 cells in those with microsatellite stability." (PMID 34848830, 2021). "In addition, oncoprotein PKCε overexpression with tumor suppressor Pten deficiency boosts the expression of CXCL13 individually and synergistically through the non-canonical NF-κB pathway." (PMID 34947813, 2021). "Furthermore, the in vitro Transwell assay and in vivo xenograft tumor mouse model were used to confirm that EGFR-CXCR5-CAR-T exhibits a significant increase in T cell infiltration to CXCL13-expressing tumors and eradicates the CXCL13-expressing tumors more efficiently." (PMID 34553036, 2021). "Finally, co-staining the tissue section used for the Vectra mIHC experiment with an anti-CXCL13 antibody by standard IHC, followed by co-localization analysis of tumor cells and CXCL13-positive cells, provided visual confirmation that tumor cells are the primary expressors of CXCL13." (PMID 34795254, 2021). "We also observed a substantially lower level of CXCL13 expression in EGFR-MT than in EGFR-WT tumor, which further supports the hypothesis that CXCL13-producing TFH-like cells contribute to the anti-PD-1 response through recruiting B cells to functional TLS in tumors." (PMID 34663810, 2021). "Finally, IHC analysis was performed to detect the Ki67 and E-cadherin expression, which revealed that CXCL13 promoted the tumor Ki67 expression and reduced E-cadherin expression, while A3149 inhibited CXCL13’s promotion of tumor Ki67 expression and the inhibition of E-cadherin expression." (PMID 34922542, 2021). "Moreover, these genes may play important roles in promoting tumor angiogenesis (CXCL13, ZAP-70, and CCL19), tissue remodeling (ITGAM and ITGB2), and immunosuppression (CD4 and IL-10) in cancer cell lines or samples." (PMID 32509861, 2020). "Also, CXCL13 can initiate a positive feedback loop for B cell activation so it may useful to deliver CXCL13 into the tumor to enhance TIL B cell antitumor functions." (PMID 33193299, 2020).
tumor (continued). "Similarly, CXCL13's role in tumor immunity is contradictory." (PMID 33193299, 2020). "And GSEA analysis showed CXCL13 might play an important role in tumor migration." (PMID 32669964, 2020). "In summary, tumor cells may utilize CXCL13 to promote growth, invasion, and metastasis." (PMID 33193299, 2020). "Additionally, CXCL13 may be utilized to improve the antitumor immune response by increasing B cell localization to tumor site." (PMID 33193299, 2020). "In addition, it has been observed that the expression of TFH gene reflects the formation of TLS in tumor microenvironment, while the use of cytokines such as CXCL13 and lymphotoxins in tumor microenvironment also stimulates the TLS formation and promotes the recruitment of immune cells." (PMID 31662750, 2019). "Also in the CD4+ T cells, expression of CXCL13 appeared to be biased to the tumor fraction." (PMID 30505306, 2018). "These CXCL13-expressing FDCs were found to colocalize with CXCR5+ follicular helper T cell-like cells, suggesting that CXCL13 expression in tumor TLSs could contribute toward generation of humoral immune responses via recruitment of CXCR5+ immune cells into the GC." (PMID 29312327, 2017). "First, tumor nodules in histologic sections of mice upon BaP treatment were analyzed as described, and the results showed that at treatment time points of 120 days, 180 days, and 240 days, Cxcl13-/- mice had much fewer lesions than Cxcl13+/- and Cxcl13+/+ mice." (PMID 26565418, 2015). "Notably, the results showed that CXCL13 mRNA expression was obviously correlated with tumor grade, lymph node status or ER status; CXCL13 mRNA expression was significantly up-regulated in grade 2/3 (P = 0.046/ P = 0.035), lymph node positive (P = 0.012) or ER negative group (P = 0.005)." (PMID 25990390, 2015). "However, the strong correlation of serum CXCL13 with the GPS as well as high tumor burden such as stage and EBV DNA might influence their prognostic value in the multivariate analysis." (PMID 25966773, 2015). "CXCL12 (SDF-1) and CXCL13 (BLC) and their respective receptors CXCR4 and CXCR5 have been implicated in tumor growth, metastasis, and are critical for the regulation of the tumor microenvironment in multiple cancer sub-types as a component of the tumor “Immunome”." (PMID 24795716, 2014). "Thus, the CXCL13/CXCR5 axis might be pivotal factors for the Tfh/B cell infiltration into tumor sites and subsequent tumor formation." (PMID 24966464, 2014). "The fact that pre-incubation of 2F7 cells with neutralizing antibody to CXCR5 substantially delays the time to death in the model provides additional evidence that the CXCR5/CXCL13 axis could potentially be playing an important role in tumor development in the model." (PMID 23936541, 2013). "However, we found a strong cytoplasmatic expression of CXCL13 in epithelial tumour cells, which was comparable with levels found in lymph follicles of draining lymph nodes from the same patients determined to be free of tumour." (PMID 18781150, 2008). "For example, Cr3+ can increase the expression of CXCL13 and CCL3 chemokines, thereby generating tertiary lymphoid structures in tumor, which promotes the infiltration, migration, and anti-tumor efficacy of CAR-T cells." (PMID 41355954, 2026). "EATL containing more abundant macrophages was enriched in inflammatory response signatures, with upregulation of CD274, CXCL13, and IDO1 transcripts, suggesting an immunosuppressive tumor microenvironment." (PMID 41057685, 2026). "Mechanically, in vitro and in vivo experiments validate that valerate-induced upregulation of GABBR1 stimulates the secretion of CXCL13, which in turn promotes robust infiltration and activation of CD8+ T cells within the tumor microenvironment." (PMID 42157924, 2026). "Promoter hypomethylation in tumor tissues correlated with overexpression of LAMC2, CTHRC1, CXCL13, FST, SPP1, and PLAU, whereas CDKN2A showed hypermethylation." (PMID 41776121, 2026).
tumor (continued). "EATL is characterized by strong inflammatory activity, with enriched gene sets like interferon response and IL-6/JAK/STAT3 signaling and overexpressed inflammation-related genes (e.g., PD-L1, CXCL13), suggesting STAT3-driven tumor-promoting inflammation." (PMID 41057685, 2026). "Here, we identify NSCLC-specific overexpression of the CXCL13 and CCL20 chemokines within the tumor microenvironment (TME) and develop a dual chemokine receptor strategy to overcome this barrier." (PMID 40764989, 2025). "Chemokines such as CXCL4, CXCL9, CXCL10, CXCL11, CXCL13, and CCL5 contribute to the accumulation of CD8+ T cells and B lymphocytes in tumor tissues and inhibit angiogenesis." (PMID 41223031, 2025). "Antigen-pulsed engineered DCs induced significantly higher IFN-γ secretion and tumor cell killing than single-gene DCs, indicating the requirement of CD93, CD40L, and CXCL13 combination for optimal T cell activation and antitumor effects." (PMID 40733726, 2025). "We further performed mIF on tumor tissue samples before and after NAIC to detect the dynamic changes of CD4+CXCL13+ cells upon treatment." (PMID 40295492, 2025). "The expression of three transgenes in the Engineered DCs leads to significant tumor reduction in both generations of Engineered DCs, showcasing the importance and role of the immune-modulating properties of CD40L, CD93, and CXCL13." (PMID 41295503, 2025). "In this study, we identified a higher proportion of CXCL13+ CD4+ and CD8+ T cell subsets in pre-treatment tumor tissues, which correlates with recurrence of CSCC." (PMID 40464813, 2025). "By guiding these immune cells to the TME, CXCL13 plays a crucial role in the development and maintenance of TLS, thereby influencing the overall immune landscape and response within the tumor." (PMID 40352278, 2025). "Other upregulated genes included NR3C1, NMB, and COTL1, which are coordinately expressed with PDCD1, CXCL13, and ENTPD1 by tumor infiltrating CD4+ T cells." (PMID 40956619, 2025). "In oral squamous cell carcinoma, CXCL13 activates c-Myc, thereby enhancing RANKL generation in stromal and preosteoblastic cells within the tumor–bone microenvironment." (PMID 41583429, 2025). "In tumors, while blood-TCR-matched CD4+ cells also showed high frequencies of CXCL13+ and Tregs, this is because they were also prevalent among total CD4+ cells, indicating their basal contribution to the immune tumor microenvironment." (PMID 40299576, 2025). "The trivalent Cr3+ ions, which are the major degradation product of these nanocomposites, can increase the CXCL13 and CCL3 chemokine expressions to generate tertiary lymphoid structures (TLSs) in the tumor tissues, facilitating the CAR‐T cell infiltration." (PMID 38899741, 2025). "Preclinical models have demonstrated that the CXCL13/CXCR5 axis is crucial for promoting intra-tumour T-cell migration, and accordingly, tumours with high CXCL13 expression exhibit an increased infiltration of activated CD8+ CXCR5+ T-cells." (PMID 40361472, 2025). "Elevated CXCL13 secretion, in turn, enhances tumor growth, migration, and invasion through CXCR5 on the tumor cell surface." (PMID 40406143, 2025). "To assess the impact of CXCL13 on in vivo CAR T cell migration, we analyzed the distribution of CAR T cells in tumor‐bearing mice seven days after adoptive transfer." (PMID 40492496, 2025). "In a pan-tumor meta-analysis investigating T-cell mechanisms in sensitization to checkpoint inhibitors (CPI), intra-tumoral infiltration of CD8+ CXCL13+ cells has been described as a favorable indicator of response to immunotherapy." (PMID 40806532, 2025). "Another signature chemokine (CXCL13) and its receptor (CXCR5) were detected in B cell-rich zones of tumor/TLS sections." (PMID 39827246, 2025).
tumor (continued). "The identification of a TIGIT+PD-1+CXCL13+ CD8+ T cell subset—characterized by features of both function and tumor reactivity—highlights a critical population shaped by chronic antigen exposure and enriched particularly in MSI CRC patients." (PMID 40799645, 2025). "These myCAFs exhibited strong interactions with cytotoxic T/NK cells through the ICAM1, CD55, CXCL13, and CXCL16 signaling pathways, suggesting a potential contribution to tumor regression." (PMID 40107247, 2025). "They discovered that CXCL13+ T lymphocytes were more prevalent in ATC, potentially enhancing the tumor's sensitivity to immunotherapy." (PMID 39744583, 2025). "CD4+ CXCL13+ Tfh cells and CD8+ CXCL13+ T cells predominantly expanded among ICB-Rs, which we termed IRATs as tumor-responsive T cells (TRTs)." (PMID 40054456, 2025). "In a B16-OVA melanoma mouse model, sustained delivery of CXCL13 and LIGHT induced mature TLS formation, enhanced antigen-specific T-cell activation, and significantly inhibited tumor growth." (PMID 41590037, 2025). "By analyzing the bioinformatics database and verifying the cancerous and non-cancerous tissues of different patients, we found a significant upregulation of CXCL13 and CCL20 in NSCLC versus normal lung tissue, establishing a tumor-directed chemokine gradient." (PMID 40764989, 2025). "We quantified the spatial localization of CXCL13 + CD8+ and CXCL13 − CD8+ cells inner-, peri-, and outer-region of the tumour." (PMID 40670667, 2025). "CXCL13 secreted by these TRM‐like CD8+T cells promotes B cell recruitment and TLS formation in the tumor microenvironment." (PMID 41361844, 2025). "C-X-C motif chemokine ligand 13 (CXCL13) is a crucial chemokine for the recruitment of immune cells and the formation of tertiary lymphoid structure (TLS) in the tumor microenvironment." (PMID 40352278, 2025). "Through evaluation of CXCL13+ cells (normalized count > 0) within the Treg/Tfh cluster we found that CXCL13+Tfh were almost exclusively found in TME (Blood: 2/14583; Tumor: 121/2182 CXCL13+ cells)." (PMID 39932553, 2025). "Our findings revealed that the PR-enriched genes were associated with tumor specific T cells, and PR patients displayed higher abundance of tumor specific T cells, evidenced by elevated levels of CD8A, CXCL13, and IFNG genes." (PMID 41422078, 2025). "Accumulated tumor antigen-specific LIGHT+CXCL13+IL-21+ Tfh cells and TLS decreased tumor growth in a CD4+ T cell and CXCL13-dependent manner." (PMID 40475770, 2025). "Consistent with previous findings, we observed that Tcr-1-positive CD8+ subclone was identified as high expression of GNLY, ZNF683, CXCL13, and were furtherly proven of high avidity against SYT-SSX fusion-positive tumor cells." (PMID 39748060, 2025). "Tumors characterized by a high mutation load and rich in CD8+ T cells exhibit elevated levels of CXCL13 and CD103, correlating with significantly increased B cell presence across various tumor types." (PMID 39926286, 2025). "CD8+ T cells that exhibited high expression levels of exhaustion gene (HAVCR2, ENTPD1, LAG3, PDCD1, CXCL13, TOX, and GZMB) in the primary tumor were extracted and clustered." (PMID 40364834, 2025). "One patient with a stage T3 tumor had a T follicular helper (TFH) cell phenotype of CD10+, CXCL13+, PD1+, and BCL6+." (PMID 40427170, 2025). "Visium and Slide-seq overlays show that PD-L1-high tumour islands frequently abut VEGFA-rich peri-necrotic belts, while CXCL13+ tertiary lymphoid structures reside millimetres away yet harbour distinct cytokine profiles." (PMID 40959084, 2025). "Based on these clinical values of TLS, we can directly inject specific cytokines (such as CXCL13 and CCL21) into the tumor to promote immune cell infiltration, TLS formation, and tumor shrinkage." (PMID 40612858, 2025).
tumor (continued). "The interaction between T follicular helper cells and B cells can promote immune-activated germinal center response, which further activates CCL19-21/CCR7 axis and CXCL13/CXCR5 axis and promotes tumor development 50-52." (PMID 39895788, 2025). "Given that CXCL9 and CXCL13 expression appears to be induced by anti-PD-L1-CRT and that these cells localize to the vicinity of the tumour, we next sought to identify these cell types through the expression of genes that identify cell types." (PMID 40670667, 2025). "Generally, our research revealed the direct role of RBM47 in suppressing CC and modulating CXCL13 within TLS, emphasizing the significance of RBM47 in promoting anti-tumor immune responses and impeding tumor advancement." (PMID 38914961, 2024). "Several of these chemokines including CCL21 (~224-fold) and CXCL13 (~66-fold) were previously shown to exert immunosuppressive effects by recruiting CD4 and CD8 T cells and DC in the TME, thereby inhibiting tumor progression and metastasis." (PMID 39766038, 2024). "The qRT-PCR results showed that CXCL1, PIGR, and TNFRSF14 were significantly lower expressed in BC tissues than adjacent tissue, while CXCL13 and NKAIN were significantly upregulated in BC tissues compared with adjacent tumor tissue." (PMID 39287311, 2024). "This study was pioneering in conducting a Pan-Gyn analysis based on CXCL13 expression and revealed that CXCL13 can serve as a prognostic factor, concurrently playing a pivotal role in TIME by influencing tumor-infiltrating immune cells and apoptotic pathways." (PMID 38459390, 2024). "The combination of FAK knocking down and a TIGIT-blocking antibody significantly elevated CXCL13 production and the formation of TLS which lead to reduced tumor burden and increased survival in mice KMF ovarian tumor model." (PMID 39569184, 2024). "CXCL13+ CD8+ T-cells were primarily found in tumors 1 and 4, and in both we see a strong tendency for these cells to co-locate near tumor cells." (PMID 38712065, 2024). "Chemokine (CXCL13)-high-expressing T cells are also believed to be critical for TLS maturation, thereby influencing tumor progression." (PMID 39620224, 2024). "CXCL13, a ligand of the CXCR5 receptor, is a chemotactic protein for B cells that recruits CXCR5+ B cells to tumor tissues, thereby enhancing tumor immunity." (PMID 39611128, 2024). "Tumor-specific T cells highly expressed CD27, IFNG, GZMB and CXCL13 and secreted more effector cytokines for tumor cell killing, as validated experimentally." (PMID 39033098, 2024). "In advanced gastric adenocarcinoma (gastric signet ring cell carcinoma), enhancing CD8+ T cells’ ability to produce CXCL13 can stimulate TLS formation in patients, exerting anti-tumor effects." (PMID 39840050, 2024). "The CXCL13/CXCR5 axis has been identified as a key mediator of pro-tumorigenic immune responses, facilitating the recruitment of immunosuppressive cells to tumor sites." (PMID 39835121, 2024). "Significantly, CXCL13 levels were diminished in both serum and RFA-treated, neutrophil-depleted tumors, suggesting that a decrease in this chemokine might be linked to mitigated tumor growth and emphasizing the significance of neutrophils in the systemic anti-tumor response following RFA." (PMID 39351436, 2024). "Tumor-infiltrating CD4+ and CD8+ T cells usually express the B cell-recruiting C-X-C motif chemokine ligand 13 (CXCL13), possibly to request B cells help." (PMID 38629061, 2024). "Our results revealed that PD1+CXCL13+CD8+T cells exhibited enhanced E:T ratios, indicating a stronger anti-tumor capacity against HNSCC cells." (PMID 39493749, 2024). "We found that the addition of MSCs to a tumor cell culture induced the expression of chemokines CXCL1, CXCL5, and CXCL13." (PMID 38182756, 2024).